RARB (retinoic acid receptor beta)
Diseases named in the same sentence as RARB in open-access papers (continued):
Sharing a sentence is not in itself a finding about the gene and the disease.
cancer (continued). "Although most malignant cells have a very low level of RARβ expression, retinoid-sensitive cancer cells are characterized by a marked induction in endogenous RARβ expression after retinoid treatment in vitro." (PMID 22087283, 2011). "Only APC (39%), CCND2 (21%), CDH1 (7%), and RARB (4%) were hypermethylated in >2% of these cancer-free subjects." (PMID 21577262, 2011). "As for RXRβ, although its expression was found stable in normal lung cells and cancer lines, a concomitant down-regulation was observed with RARβ in SqCLC samples." (PMID 19961602, 2009). "Downregulation of mRNA expression of RARβ often observed in cancer cells has been considered as a cellular mechanism to prevent retinoid-induced growth arrest." (PMID 17767717, 2007). "Expression of RARα and RARβ were found in three and seven cancer tissues, respectively, and levels of RXRα mRNA were significantly decreased in poorly differentiated cancer tissues." (PMID 10389997, 1999). "Expression of RARα, RARβ, RARγ, RXRα and RXRβ was found in most cell types in gastric mucosa tissues from normal individuals as well as in distal normal tissues from cancer patients." (PMID 10389997, 1999). "RARB and VDR are specific types of these receptors that have been implicated in cancer." (PMID 40334012, 2025). "Thereinto, RARB was found to be involved in multiple cancer-related pathways." (PMID 40371351, 2025). "RARβ mRNA was either undetectable or present at low basal levels while RARα and RARγ mRNAs were each expressed at readily detectable basal levels in these examined cancer cell lines." (PMID 37689790, 2023). "Methylation of RARB promoter would condition a favorable environment for cancer progression." (PMID 37548362, 2023). "In a ferret model that was given β-carotene supplements and exposed to cigarette smoke for 6 months, the results showed that β-carotene inhibited retinoid signaling by decreasing the RARβ gene expression and amplifying the expression of activator protein-1, thereby promoting cancer formation." (PMID 36118777, 2022). "On the other hand, RARβ antagonist (LE135) induced a potentiation of ATRA effect treatment on cancer stem cell self-renewal indicating that RARβ might function as a buffer for retinoic acid response on cancer stem cell population." (PMID 33723318, 2021). "To confirm cancer-cell content in our low-volume primary tissue specimen, we have developed a multiplex epigenetic biomarker assay to detect promoter methylation of PC-associated genes including GSTP1, RASSF1, RARb and APC." (PMID 34581895, 2021). "Besides that, RARβ is frequently lost early in carcinogenesis by epigenetic silenced, which is probably an important reason for the RA resistance in carcinoma." (PMID 32238162, 2020). "RARβ exerts an inhibitory effect on expression of viral oncoproteins E6 and E7 thus decrease in RARβ leads to the development of pre-neoplastic cervical lesions and cancer." (PMID 30803219, 2019). "RARβ is epigentically altered in many different kinds of human cancers." (PMID 28008143, 2017). "Cancer cells may silence or repress RARβ by mechanisms other than hypermethylation in NSCLC in order to initiate and promote their growth and resist treatment with RA." (PMID 28008143, 2017). "A significant number of human cancers exhibit aberrant expression of RARB gene." (PMID 27011326, 2016). "Hypermethylation of APC, CCND2, GSTP1, PTGS2 and RARB was highly cancer-specific." (PMID 26086362, 2015). "The RARβ has become a particularly interesting target in cancer research." (PMID 24720764, 2014). "During cancer progression, RARβ gene deletion or promoter hypermethylation frequently occurs." (PMID 24720764, 2014). "Additionally, induction of HOXA5 is important for retinoic acid (RA)-mediated apoptosis and cellular growth inhibition acting directly downstream of RARβ, and plays an important role in RA-mediated anti-cancer activity." (PMID 22876840, 2012).
cancer (continued). "Thecombination of RXR ligand with ciglitazone also cooperatively inhibits thegrowth of breast cancer and lung cancer cells by activating the RARE promoteractivity and inducing RARβ,which plays a critical role in mediating the growth-inhibitory effects ofretinoids in various cancer cells." (PMID 18528526, 2008). "This enzyme might mediate the promotion of colon carcinogenesis by metabolic disorders and inflammation and several lines of evidence indicate that COX-2 might be regulated by PPARγ and RARβ activation in cancer cells although the mechanism is unclear." (PMID 17767717, 2007). "Transcriptomics and proteomics as a whole identified key DEPs of the THRB(−/−)/RL95-2 cells, including cellular junctions, metabolism, and cancer-related pathways, suggesting RARβ, CRABP2, and RXRA could be potential targets for MPA resistance and targeted by CANA." (PMID 40371351, 2025). "However, the function of RARβ in cancer stem cells (CSCs) has yet to be determined." (PMID 33995625, 2021). "Following surgical resection for CRC, Kaplan–Meier survival curves showed that RARβ-positive tumors and early-stage cancer (TNM stage I) were associated with longer overall survival compared with RARβ-negative tumors and advanced cancer (TNM stages II–IV) in CRC patients." (PMID 30944670, 2019). "However, it has been recently reported that RARβ could also play a role in mammary gland tumorigenesis, thus demonstrating the important but yet incompletely understood function of this receptor in cancer development." (PMID 25933005, 2015). "For the remaining 17 genes, DNMT3B, RARB, SMAD5, SMARCA5, SMARCC1 and TGFBRAP1 were predicted only by our method, but various evidence suggests that they have a driving role in cancer development." (PMID 39186807, 2024). "Antagonism, for most of the selected targets (genes in purple), and agonism, for RARA, RARB, and ADRA2C (genes in red), were proposed as potential approaches for anti‐aging and anti‐cancer treatment." (PMID 37888486, 2023). "Following RARβ silencing, the down-regulation of cancer-related genes, ALDH1A1, CYP24A1, BIRC5, EDN1, IL-1β and PTGS2 in A549 parental cell suggest the importance of RARβ in controlling the expression of genes related to carcinogenicity." (PMID 33995625, 2021). "Instead, the analysis showed that cancer stage was affected by HIV status (χ2 = 19.93; P = 0.001), RARB (χ2 = 7.32; P = 0.002), and CADM1 (χ2 = 12.68; P = 0.013) methylation status." (PMID 33718129, 2021). "Agreement with our results, GSK-3β was higher and RARβ lower in HCC than adjacent liver tissue, which phenomenon was also observed in many other malignant tumors." (PMID 31938062, 2020). "The expression of RARβ as well as RXRβ was reported to be downregulated in NSCLC, which enabled the cancer cell to evade apoptosis." (PMID 32293355, 2020). "Our study strongly supports the druggability of NRs in TME, notably AR and RARβ, which can mediate a CAF-directed cancer therapy." (PMID 30925918, 2019). "Cancer markers previously used to detect MRD are predominantly methylated in epithelial and intermediate cell lines, with RASSF1A, TWIST1, and RARβ methylation covering more of the epithelial–mesenchymal spectrum in the cell line panel." (PMID 30154364, 2018). "By targeting RARB, a specific biomarker of the GC_P02T subcluster, it is possible to modulate the MAPK signalling pathway, which in turn can influence the apoptotic and differentiation processes of cancer cells." (PMID 39877290, 2025). "Furthermore, in cancer cell lines, EGCG inhibits DNMT’s activity and reactivates methylation-silenced genes, such as p16INK4a and retinoic acid receptor beta (RARβ)." (PMID 38004113, 2023).
cancer (continued). "In contrast, APC, DAPK1, IGSF4, RARB, and TIMP3 genes were found to be methylated in cancer cells." (PMID 34552632, 2021). "With the exception of three clusters of NRs representing NR classes I (cluster I: RORC, VDR, PPARA, NR1D1, THRA, RORA, NR1H3; cluster II: RARB, PPARG, THRB) and III (cluster III: ESR1, PGR, AR, ESRRG), NR class was not a good determinate of NR expression patterns in the different cancer types." (PMID 32024906, 2020). "For example, for the two miRNA pairs that both are members of the miR-15 family (miR-15a/b), the top three possible co-functional targets for the non-cancer diseases are IFNG, MTHFR, RARB, while for cancers are BCL2, CDKN1A and CCND1." (PMID 28340554, 2017). "Epigenetically silenced RARβ has been shown to be re-expressed in the presence of histone deacetylase (HDAC) inhibitors and DNA methyltransferase inhibitors (DNMT) inhibitors in RARβ2 silent cancer cells." (PMID 28008143, 2017). "Moreover, alterations in the expression or activity of specific retinoic acid receptors (RARA, RARB, and RARG) were well-known TFs controlling transcription and inducing diverse types of cancer by recruiting different co-regulator complexes." (PMID 29033978, 2017). "So far, mechanisms leading to reduction of RARB expression in cancer tissues have not been thoroughly understood." (PMID 27011326, 2016). "RARB methylation also appears to be very specific for cancer as none of the normal tissues assayed in our study possessed a RARB MI above 4%." (PMID 25826459, 2015). "Others like GRASP, HEMK1, RARB and SLC16A5 were methylated mostly in histologically detectable cancer and may represent later events." (PMID 25548652, 2014). "Of note, this finding indicates that RARβ promoter methylation may not be specific to cancer cells and can also occur in the surrounding healthy tissues." (PMID 38067304, 2023). "Moreover, we found that treatment with the p38-specific agonist Dehydrocorydaline restored the proliferation, whereas suppressed the apoptosis of cancer cells induced by DLEU2 knockdown, which confirmed that the DLEU2/RARB axis regulates CRC tumorigenesis by manipulating the MAPK signaling pathway." (PMID 35611845, 2022). "RARB showed nearly absent methylation in benign samples; cancer samples showed slight methylation." (PMID 29851970, 2018). "The heterogeneity of cancer cells in parental cells containing a mixture of CSC populations has shown a clear indication that the silencing of RARβ might have affected other CSCs populations, but not the CSC that shown positive for CD166+EpCAM+ and CD166-EpCAM-." (PMID 33995625, 2021). "Exogenous RARβ in RARβ-negative cancer cells restored ATRA-induced growth inhibition and apoptosis, whereas RARβ antagonists or antisense mRNA in RARβ-positive cancer cells blocked the effect of ATRA." (PMID 24116031, 2013).
adenocarcinoma (6 papers, 2008 to 2017). A common cancer characterized by the presence of malignant glandular cells. "As matter of fact, CRBP-1 transfection increased proliferation, up-regulated RAR-α and down-regulated RARβ expression in A549 adenocarcinoma cells." (PMID 26807202, 2015). "The adenocarcinomas analyzed showed hypermethylation for both, RARB and RASSF1A genes." (PMID 18702824, 2008).
infection (5 papers, 2020 to 2025). The state of being infected such as from the introduction of a foreign agent such as serum, vaccine, antigenic substance or organism. "Consequently, the targeted inhibition of RARβ expression may serve as a promising therapeutic approach for modulating intestinal Th17 cell-mediated immunity in the context of infection or inflammation." (PMID 40801260, 2025). "Similarly, little is known about the role of RARβ in the regulation of autophagy during infection." (PMID 32867365, 2020). "Three weeks after infection with AAV-RARE in the ACC of sham- and SNI-treated mice, immunofluorescence staining revealed that both GFP and RARB expression was significantly lowered after SNI treatment, further confirming the downregulated RA and RARB after nerve injury." (PMID 40591414, 2025). "To support the functional relevance of RARβ induction, we silenced the retinoid-receptor in HCC-1599 and MB-157 cells by stable infection of retroviral constructs containing two distinct shRNAs targeting RARβ (shRARβ-a and shRARβ-b) and a control shRNA (shCTRL)." (PMID 33081033, 2020).
neurodegenerative disease (2 papers, 2024 to 2025). A disorder of the central nervous system characterized by gradual and progressive loss of neural tissue and neurologic function. "It is also worth noting that in some neurodegenerative diseases, RARβ signalling has been shown to have therapeutic benefits in rodent models of these diseases." (PMID 39228795, 2024).
peripheral neuropathy (1 paper, 2025). A disorder affecting the peripheral nervous system. "Taken together, we infer that overexpression of cingulate RARB contributes to normalizing the abnormal structural and functional plasticity of pyramidal neurons after peripheral neuropathy." (PMID 40591414, 2025). "These behavioral results suggest that RARB supplementation in the ACC relieves pain hypersensitivity and associated anxiodepression induced by peripheral neuropathy." (PMID 40591414, 2025). "RARB as a transcription factor is decreased in the ACC after peripheral neuropathy." (PMID 40591414, 2025). "Overall, we inferred that exogenous supplementation of RARB normalized abnormal structural and functional plasticity of ACC pyramidal neurons after peripheral neuropathy, which in turn produced analgesic, anxiolytic, and antidepressive effects." (PMID 40591414, 2025).
renal diseases (1 paper, 2012). "There were some reports studying the association of RARβ expression with renal diseases." (PMID 23203050, 2012). "Further studies for the relationship between RARβ and the renal diseases should be conducted in the future." (PMID 23203050, 2012).
RARB also shares sentences with these, for which no sentence is quoted: Obesity (5 papers); leukemia (4); benign prostatic hyperplasia (3); prion disease (3); bladder (2); cholangiocarcinoma (2); ductal carcinoma in situ (2); gastric tumor (2); head and neck cancer (2); invasive carcinoma (2); lung (2); Neurodevelopmental delay (2); squamous cell tumors (2); uveal melanoma (2); acne (1); Alcohol (1); amyotrophic lateral sclerosis (1); anal carcinoma (1); attention deficit-hyperactivity disorder (1); autoimmune lymphoproliferative syndrome (1); basal cell carcinoma (1); bipolar disorder (1); bradyopsia (1); cannabis dependence (1); carcinoma in situ (1); cardiovascular diseases (1); cataract (1); cervical squamous cell carcinoma (1); Chorioretinal coloboma (1); chronic lymphocytic leukemia (1).
A further 56 diseases each share a sentence with RARB in 1 paper.